CD4 (CD4 molecule)
Diseases named in the same sentence as CD4 in open-access papers (continued):
Sharing a sentence is not in itself a finding about the gene and the disease.
tumor (continued). "CD4+ T cells may also be working via direct cellular interactions with the tumor cells or host stromal cells in the tumor microenvironment." (PMID 25089198, 2014). "CD4+ T cells also played a role in tumor immunosurveillance." (PMID 24884733, 2014). "However, tumor-specific CD4+ T cells can be rendered tolerant (anergic) when they encounter antigen in absence of a costimulatory signal." (PMID 24693228, 2014). "DCs are potent activators of regulatory CD4+ CD25+ Foxp3+ regulatory T-cells that might downregulate an efficient anti-tumor response." (PMID 25340039, 2014). "The CD4+ T cells are likely to contribute to tumor regression through many mechanisms." (PMID 25089198, 2014). "This Treg subpopulation was enriched in the peripheral blood of CRC patients, which correlated with tumor progression, suggesting that CD4+Foxp3+LAP+ Tregs may have clinical application as markers of tumor-specific Tregs in CRC patients." (PMID 25268580, 2014). "Importantly, adoptive cell transfer of CD4+ T cells from cured mice into naïve recipients was sufficient to protect the animals from tumor take." (PMID 24600588, 2014). "Vaccination with tumor lysate-loaded DCs induced tumor-reactive CD4+ and/or CD8+ T cell responses." (PMID 25694811, 2014). "Furthermore, after 1 day co-culture with tumor cells, the co-cultured naïve CD4+ T cells also displayed a significant increase in cAMP level." (PMID 25231413, 2014). "However, recent evidence suggests the importance of CD4 T helper cells in the anti-tumor immune process." (PMID 24690990, 2014). "Ligation of OX40 clearly dramatically enhances the number of effector CD4+ T cells, which may enhance tumour clearance." (PMID 24771127, 2014). "Notably, we also observed these potent cell-mediated immune responses and antitumor effects in CD4-depleted tumor-bearing mice." (PMID 24594273, 2014). "Furthermore, preliminary data from one clinical study revealed a significant decrease in Treg relative to CD4 positive cells within the tumor following intraprostatic administration of PROSTVAC-F." (PMID 25328681, 2014). "In line with this notion, our results clearly show that the combination of 2-DG and radiation elicits anti-tumor immune response by not only restoring the levels of CD4+ cells, but also the levels of molecules related to its signaling i.e. CD44, CD69, CD45, TCR-β, TCR-γδ and CD28." (PMID 25248151, 2014). "Moreover, naïve CD4+ T cells in TCR-transgenic mice conferred protection against tumor development upon subcutaneous (s.c.)injection of tumor cells." (PMID 24782871, 2014). "However, during tumor formation and development the balance of CD4+IL-17+ Th17 and CD4+CD25+Foxp3+Treg can be disrupted by inflammatory cytokines." (PMID 24949077, 2014). "Thus, initial optimal triggering of the adaptive immune response against the tumor prevented the increase of a crucial cellular component with suppressive function on CD4+ TH cells and with pro-tumor behavior on tumor microenvironment." (PMID 24600588, 2014). "IL-12 plays a key role in the activation of Th1 CD4 T cells, and we have previously demonstrated that the addition of exogenous IL-12 can partially restore CD4 T cell responses and tumor immunity in aged tumor-bearing animal." (PMID 24682539, 2014). "In addition to evaluation of SA-β-Gal expression in tumor-treated CD4+ T cells, we investigated the effects of TLR8 signaling on the expression of other senescence-associated markers and function of tumor-induced senescent T cells." (PMID 25231413, 2014). "To do this we have developed a system of 11 ordinary differential equations including the movement, interaction, and activation of NK cells, CD8+T-cells, CD4+T cells, regulatory T cells, and dendritic cells under the presence of tumor and cytokines and the immune interactions." (PMID 25140193, 2014).
tumor (continued). "Help provided by CD4+ T cells stimulates the expansion of a heterogeneous immune population of effector cells that are able to target different facets of tumorigenesis, acting together against tumor growth." (PMID 24830315, 2014). "Indeed, potent inhibition of T cell proliferation by 4T1 tumor-derived GR1CD11b cells was observed with a (1:1) mixture of CD4+ T cells and GR1CD11b cells." (PMID 24589997, 2014). "In addition, CD4+CD25+ Tregs increase at tumor sites in mice and humans during lung, head and neck, breast and ovarian cancers." (PMID 24642245, 2014). "This tumor subtype-independent association between pCR and a higher effect of chemotherapy on tumor infiltration was also found for two particular lymphocyte subpopulations: CD4 (P = 0.001; OR = 15.02, 95% CI: 2.89 to 77.92) and CD20 (P = 0.002; OR = 11.87, 95% CI: 2.47 to 57.01)." (PMID 25432519, 2014). "Flow cytometric analysis revealed heterogeneity in the tumor phenotype with respect to expression of CD4 and CD8 with tumor cells isolated from the thymus, spleen and bone marrow expressing both CD4 and CD8 or only CD4 with decreased levels of expression of CD44 and CD25." (PMID 24586935, 2014). "In patients with localized bladder cancer who were treated with preoperative ipilimumab, CD4+ T cells from the peripheral blood and tumor tissues were found to have increased expression of ICOS (inducible costimulator) compared to patients who did not receive ipilimumab." (PMID 24883190, 2014). "We conclude that a CD4+-assisted B-lymphocyte response and a robust activation of tumor-specific cytotoxic T-cells might cooperate in the anti-tumor cell immunity, induced by the D2SC/1–MethA cells." (PMID 25340039, 2014). "Phenotypic analysis of TILs demonstrated that the endogenous immune response to the tumor is weak in this model, although a low percentage CD4 and CD8 T cells could be detected." (PMID 25328681, 2014). "TSLP may have an important role in tumor progression by activating CD4+ T cells, inducing the expressing of OX40L in dendritic cells (DCs), and producing Th2-type cytokines and B-cell growth factor." (PMID 25075970, 2014). "The use of vaccines based on tumor-loaded DCs or short- plus long-peptide mix to favor helper CD4+ T-cell responses could further improve immunogenicity and clinical efficacy." (PMID 24726012, 2014). "The possibility to recruit CD4+ T cells using an anti-tumor receptor is appealing as they may support CTL anti-tumor response." (PMID 25431955, 2014). "Notably, cAMP levels in CD4+ T cells markedly decreased if the tumor cells were pretreated with the pharmacological inhibitors of 7-ddA and H89." (PMID 25231413, 2014). "Spearman’s correlation analysis revealed that CD8 expression was positively correlated with CD4 expression in the tumor parenchyma and tumor stroma (correlation coefficient = 0.62 in tumor parenchyma; correlation coefficient = 0.68 in tumor stroma; both P<0.001)." (PMID 25289108, 2014). "Therefore we co-cultured splenocytes derived from healthy animals with grMDSC or moMDSC sorted from spleens of AZD1480 treated MO4 tumor-bearing mice and analyzed their effect on the proliferation of CD4+ and CD8+ T cells, respectively." (PMID 25149535, 2014). "In addition, knockdown of CREB expression in CD4+ T cells with specific siRNA significantly prevented tumor cell-induced CD4+ T-cell senescence." (PMID 25231413, 2014). "Cytotoxic CD4+ T cells can directly kill MHC class II positive tumor cells." (PMID 24782871, 2014). "The presence of HLA-DQ expression in premalignant lesions and on some tumor cells appears to confer an advantage to the host in terms of restricted tumor growth _ENREF_24 and survival _ENREF_24through their role as initiators of CD4+ T helper cell responses against the tumor." (PMID 24595008, 2014). "Immunotherapy of EMT6 tumor growth was abolished by infusion of anti-CD4 mAb." (PMID 25409195, 2014).
tumor (continued). "Furthermore, the average numbers of CD8-positive T cells in the tumor parenchyma and stroma were significantly increased, compared with the average numbers of CD4-positive cells (P<0.05)." (PMID 25289108, 2014). "PD-1/PDL1 blockade may not only prevent or reverse type I NKT cell anergy and decrease suppressive activity of type II NKT cells on CD4+ T cells but it may also augment tumor immunity by preserving CD8+ T cells." (PMID 25389427, 2014). "By visualizing DTA-1 with the FITC-conjugated anti-rat IgG2b mAb, it was demonstrated that the tumor-infiltrating CD4+ Foxp3+ Treg population bound predominantly with DTA-1 at 6 hrs after i.t. injection, in parallel with the disappearance of tumoral Treg cells after treatment with DTA-1." (PMID 25105508, 2014). "However, high densities of tumor-infiltrating CD4+ CD25+ Foxp3+ Treg cells have been correlated with poor survival." (PMID 25105508, 2014). "CD8+ cells activated by CD4+ cells destroy virally infected cells and tumor cells." (PMID 24520300, 2014). "How certain CD4+ T cells promote tumor growth is still unknown, but given the potential clinical implications, warrants further investigation." (PMID 24853673, 2014). "Interleukin 17 (IL-17) is a proinflammatory cytokine produced mainly by CD4+ T-lymphocytes and may be important in tumor cell growth and progression." (PMID 24887477, 2014). "Also particularly relevant was the observation that both CD4+ T cells and NK cells are necessary for an anti-tumor response." (PMID 24830315, 2014). "Notably, in vivo VSSP reduced the tumor-induced down-regulation of CD3ζ chain on both CD4+ and CD8+ T cells." (PMID 24829762, 2014). "However, in contrast to the combined surgery and vaccine group, in which all mice eventually succumb to tumor, we observed complete tumor eradication in 60% of CD4 depleted mice following debulking surgery." (PMID 25186961, 2014). "The accumulation of TGF-β in the tumor microenvironment may promote the naïve CD4+ T cells to Tregs differentiation and development of immune tolerance." (PMID 24638085, 2014). "Cytokine mRNA was quantitated by PCR to investigate whether there were any differences in cytokine RNA obtained from blood versus tumor CD4+ T cells." (PMID 25436113, 2014). "NKG2D+CD4+ T cells with both immunosuppressive and anti-tumor activity have been described." (PMID 25286418, 2014). "Therefore, intratumoral administration of PADRE potentially can create PADRE-specific CD4+ T helper cells to further improve cross-presentation to generate tumor antigen-specific CD8+ T cells." (PMID 25531529, 2014). "Furthermore, the size of CD4+Foxp3+LAP+ Treg population was increased in tumor tissues compared to non-tumor tissues." (PMID 25268580, 2014). "There is considerable evidence to suggest that increased CD4+CD25+ T cells in tumor site might be due to either active recruitment or local differentiation." (PMID 24872958, 2014). "Next, we tested whether the CRTE6E7L2 DNA vaccine could treat TC-1 tumor-bearing mice in CD4-depleted mice." (PMID 24594273, 2014). "Thus, this approach allows for determining changes in phenotype and function of adoptively transferred HA-specific CD4+ T cells including their proliferation, depletion, state of activation, and anergy following exposure to HA antigen in tumor-bearing mice." (PMID 24693228, 2014). "Similarly, CD4 depletion during vaccination prevented any vaccine induce delay in tumor growth prior to surgery." (PMID 25186961, 2014). "Moreover, treatment with the sphingosine phosphate receptor modulator fingolimod that abrogates egress of T cells from lymph nodes led to a decreased number of Id-specific CD4+ T cells within the tumor, resulting in failure of tumor rejection." (PMID 24782871, 2014). "Besides its expression in T-regs and transiently in activated CD4+ T helper cells, the forkhead transcription factor 3 (FoxP3) has been also detected in various tumor cells, e.g. colorectal cancer and PDAC." (PMID 24797069, 2014).
tumor (continued). "During the antitumor response a small population of tumor-specific CD4 effector T cells may develop into memory T cells that retain their previous effector functions and rapidly produce effector cytokines." (PMID 23533029, 2013). "In support of this notion, we found that the depletion of CD4+ T cells one day before TC-1 tumor challenge dramatically compromised the efficacy of SA-4-1BBL/E7 vaccine as 75% mice developed tumors and succumbed to death as compared with ∼20% mice in the group without depletion." (PMID 24066030, 2013). "In this study, we report of a so far undescribed interaction between tumor cells and CD4+ T cells." (PMID 24205259, 2013). "CD4 T cells can also take on a cytotoxic phenotype, killing tumor cells directly." (PMID 23970885, 2013). "In addition, EL4 and B16 cells expressing flagellin also induced a potent anti-tumor response from CD4 and CD8 T cells." (PMID 24273542, 2013). "While nTreg develop in the thymus through a series of steps requiring specific signals and transcription factors de novo differentiation from naïve CD4+CD25(−) T cells at mucosal sites or in the tumor microenvironment also significantly contributes to the pool of peripheral Treg." (PMID 23898333, 2013). "In addition, loss of IL-27 signaling results in reduced production of IFN-γ by CD4+ T cells and enhanced generation of regulatory T cells, effects which can inhibit an effective anti-tumor response." (PMID 23554861, 2013). "In addition, we detected the GFP-positive CD11c+ DCs and CD4+ T cells in the tumor of the CMT93 and CT26 xenograft tumors in GFP-BMT mice." (PMID 24040017, 2013). "In thymus-like or tumor-like tissues, we detected a certain amount of CD4+ and CD8+ T cells." (PMID 24086471, 2013). "Hence, we assessed the efficacy of DPX-0907 in eliciting IFN-γ producing CD8+ and CD4+ T cells within vaccine dLN 8 days after immunization of late-stage tumor bearing AAD mice." (PMID 23533812, 2013). "Moreover, through PD-L1/PD-L2 expression, DC can engage the PD-1 inhibitory pathway, thus inhibiting lymphocyte proliferation and effector functions, inducing tumor-specific T-cell apoptosis and promoting the differentiation of CD4+ T-cells into Treg." (PMID 23763830, 2013). "However, direct anti-tumor effects of CD4+ T cells were strictly regulated by Tregs, which thereby contributed toward tumor progression." (PMID 22890822, 2013). "Notably, the combination of anti-CTLA-4 and GVAX vaccination significantly increased the number of tumor infiltrating CD4 T cells in the prostate gland, as compared to GVAX therapy alone." (PMID 23557194, 2013). "Although the best studied pathways of CD4 T cell-mediated help are those that promote antibody production by B cells, such cells also enhance tumor-specific CD8 T cell responses during disease progression and contribute to the maintenance of a functional memory CD8 T cell pool." (PMID 23533029, 2013). "While TNFR1-deficiency did not consistently modify the activation phenotype of tumor-infiltrating T cells, we found more CD4+ T cells infiltrating the tumors in TNFR1-deficient than in wild type mice." (PMID 24098720, 2013). "Increased infiltration of CD4+ T cells in tumours may also be due to a greatly enhanced number of Foxp3+ regulatory T cells, that would explain the insufficiency of the immune system to adequately attack primary tumours." (PMID 23349906, 2013). "However, the immuno-effector cells in the anti-tumor mechanism of the PE(ΔIII)/E7 fusion protein vaccine include CD4+ helper T lymphocytes, CD8+ cytotoxic T lymphocytes, and NK cells." (PMID 24058440, 2013). "More recently, in a large retrospective study of 212 tumor samples, the same Authors reported that in multivariate analysis the prevalence of tumor infiltrating CD4+ Thigh/CD8+ Thigh/%Treglow significantly correlated with longer survival and had a higher hazard ratio." (PMID 23950747, 2013).
tumor (continued). "Although this concept and process of cellular conversion and/or plasticity among CD4+FoxP3+ TReg cells remains controversial, it is clear that the biological properties of CD4 TReg cells and their subpopulations are heterogeneous and influenced by the tumor environment in which they infiltrate." (PMID 23533029, 2013). "Depletion of these CD8+Foxp3+ Tregs in addition to CD4+Foxp3+ Tregs might allow for antitumor cytotoxic function of CD4+ T cells and tumor rejection." (PMID 22890822, 2013). "We further speculate that the increased presence and activation of CD86+ antigen presenting cells may also increase tumor specific CD4+ T cell activation with all the downstream effects such as increased B cell help and anti-tumor antibody production." (PMID 26824927, 2013). "Why might CD4+Foxp3+ Tregs demonstrate enhanced proliferation in the tumor microenvironment compared to CD4+Foxp3− T cells?" (PMID 23874342, 2013). "Together, our data indicate that Tim-3-expressing CD4 T cells in human tumors could represent the functional regulatory T cells which contribute to the formation of the immune-suppressive tumor micromilieu." (PMID 23526963, 2013). "Similarly, depletion of CD4+ T cells before tumor challenge significantly negated therapeutic efficacy of the vaccines in both tumor models." (PMID 24066030, 2013). "Further identification and characterization of the mechanisms involved in the induction of tumor-reactive CD4 T cells with cytotoxic activities in cancer patients may offer significant advantages for future treatment strategies of human malignancies." (PMID 23533029, 2013). "Interestingly, only 1/6 long-term tumor-free mice, depleted for CD4+ T cells one day before vaccination, in the TC-1 model developed tumor when challenged with the secondary dose of TC-1 cells 60 days post-primary tumor challenge." (PMID 24066030, 2013). "Therefore, the capacity to reject tumor acquired by tumor-reactive CD4+ T cells largely depends on the direct suppressive activity of Tregs." (PMID 22890822, 2013). "Production of such cytokines leading to OC formationand activation, and osteolytic disease, is observed even before tumor cells colonizethe bone cavity, suggesting that CD4+ T cells prepare the metastaticniche for further establishment of tumor cells in the model used." (PMID 23935856, 2013). "Moreover, in vivo assessment of TDEs capacity for immunomodulation demonstrated their potential to prevent autologous tumor development, in a CD4/CD8-dependent manner." (PMID 24376443, 2013). "To determine whether the elimination of the IL-12-producing cells was due to a T cell-dependent anti-tumour immune response, we repeated these experiments using mice in which we selectively depleted CD4+ cells and/or CD8+ cells." (PMID 24251770, 2013). "It remains to be elucidated which cells of the immune system contribute to anti-cMYC-specific anti-tumor activity and whether c-MYC NHP-B specific CD4+ T-cells are required for long term tumor rejection in this model system." (PMID 24130880, 2013). "It is tempting to speculate that challenge with the TC-1 tumor expressing E7 TAA primes both CD4+ and CD8+ T cells to this TAA before vaccination." (PMID 24066030, 2013). "A wealth of historical and more recent evidence now suggests that CD4+CD25high Treg cell populations influence the presence, induction, and maintenance of protective anti-tumor immunity, and their association with the progression of malignant disease has been highlighted by a number of observations." (PMID 23378947, 2013). "Additionally, Tim-3+ Tregs specifically accumulated in the tumor nest, where Tim-3+ CD4 cells had close contact with the Tim-3 ligand galectin-9." (PMID 23526963, 2013). "Peak expansion of tumor-specific CD4+ T cells was observed 2 days later as the CD8+ T cell." (PMID 22890822, 2013).